TINAGL1 (tubulointerstitial nephritis antigen like 1)
Diseases named in the same sentence as TINAGL1 in open-access papers (continued):
Sharing a sentence is not in itself a finding about the gene and the disease.
cancer (9 papers, 2017 to 2025). A tumor composed of atypical neoplastic, often pleomorphic cells that invade other tissues. "In the tissues of DGC patients, TINAGL1 was higher in cancer than paired normal tissues and detected with collagen type I alpha 1 chain (COL1A1) in the same spot." (PMID 38355577, 2024). "TINAGL1 interacts with integrin β1 located on the membrane of cancer cells and activates the FAK signaling pathway to contribute to the progression of DGC." (PMID 38355577, 2024). "Nevertheless, our findings suggest a pivotal role of CAF-secreted TINAGL1 in mediating the interplay between CAFs and cancer cells." (PMID 38355577, 2024). "In this context it is nevertheless remarkable that the use of recombinant TINAGL1 has recently been proposed for cancer treatment." (PMID 35931808, 2022). "Recently, the correlation between TINAGL1 and several cancers was reported." (PMID 38355577, 2024). "The functional role of TINAGL1 in cancer is still controversial." (PMID 38355577, 2024). "In addition, previous studies have focused on the role of cancer cell-derived TINAGL1, but the origin of intratumor TINAGL1 remains uncertain." (PMID 38355577, 2024). "TINAGL1 siRNA also slightly reduced the expression of the mesenchymal marker Twist in cancer cells." (PMID 38355577, 2024). "Moreover, TINAGL1 was more expressed in cancer tissues of human DGC than in paired normal gastric tissues." (PMID 38355577, 2024). "Moreover, recombinant or CAF-derived TINAGL1 protein interacts with integrin subunits, especially β1, in cancer cells." (PMID 38355577, 2024). "Given the diversity of secretory factors derived from CAFs that intricately influence cancer cell progression, the influence of TINAGL1 alone may be insufficient to delineate comprehensive effects." (PMID 38355577, 2024). "We detected insertion at the intronic region of RBM4 (chr11), known to be associated with cancer and ncRNA SMG1P5 (chr16), downstream of TINAGL1 (chr1) and LOC339807 (chr2) and at an intergenic region that is 30Kb upstream of ZNF846 and 11Kb downstream of FBXL12 in chromosome 19." (PMID 28410234, 2017). "Furthermore, TINAGL1 is a secretory protein 21 and potential carcinoma tumorigenicity 25-27." (PMID 39781468, 2025). "Several studies have already discovered differential gene expression in cancer cell-lines based on global gene expression analysis, such as CYP26B1, DHRS3, and TINAGL1 were up-regulated by ATRA." (PMID 39210795, 2025). "Our data also revealed that the protein levels of TINAGL1 increased in both recombinant TINAGL1-treated and CAF-co-cultured cancer cells." (PMID 38355577, 2024). "Our findings suggest that interventions aimed at disrupting the TINAGL1/ITGB1/FAK axis between CAFs and cancer cells could hold therapeutic value in managing DGC patients." (PMID 38355577, 2024). "Most previous studies have focused on the expression of TINAGL1 in cancer cells themselves or could not consider the expression of host cells within tumors." (PMID 38355577, 2024). "However, we also found that CAFs without up-regulation of TINAGL1 existed, even in cancer tissues." (PMID 38355577, 2024).
lung (1 paper, 2024). "We next examined the expression of ZNF334 and TINAGL1 genes in lung specimens from C57BL/6J mice with LNM lung SCC tumorous lesions." (PMID 38637790, 2024).
vasculopathy (1 paper, 2023). "Additionally, TINAGL1 can activate the TGFβ signaling pathway and increase VEGF secretion, a mediator of SSc vasculopathy." (PMID 36835058, 2023).
TINAGL1 also shares sentences with these, for which no sentence is quoted: infection (2 papers); asthma (1); benign tumors (1); Fabry disease (1); fibrosis (1); gastrointestinal disease (1); glioma (1); lung squamous cell carcinoma (1); nephritis (1); non-small cell lung carcinoma (1).